LINC00937 (long independently transcribed non-coding RNA 937)
Gene: Long non-coding RNA gene on chromosome 12 (8,244,845 to 8,453,161, reverse strand). Ensembl gene ENSG00000226091.
Diseases named in the same sentence as LINC00937 in open-access papers:
LINC00937 is named in the same sentence as 1 disease in open-access papers, as found by Europe PMC text mining. Sharing a sentence is not in itself a finding about the gene and the disease. The quoted sentences say what the papers report.
tumor (1 paper, 2025). "Our experimental results showed that in 10 pairs of OSCC tumor tissue samples and normal tissue samples, LINC00937 is more highly expressed in OSCC tumor tissue samples and is localized in the cell nucleus." (PMID 40988926, 2025). "Among the genes comprising this NETs signature, LINC00937 was identified as a key feature gene due to its prognostic relevance and elevated expression in tumor tissues." (PMID 40988926, 2025).